DSG1 (desmoglein 1)
Diseases named in the same sentence as DSG1 in open-access papers (continued):
Sharing a sentence is not in itself a finding about the gene and the disease.
pemphigus (continued). "The novel CLIA, the first to quantify four major autoimmune blister disease autoantibodies (anti-Dsg1/anti-Dsg3/anti-BP180/anti-BP230) using a single sample tube, offers a simple and time-efficient test for diagnosing and screening pemphigus and BP." (PMID 40661962, 2025). "Yuan and colleagues recently revealed that autoreactive Dsg1 and Dsg3 specific antibody‐secreting CD19+ B cells and CD138+ plasmablasts are more prevalent in lesional skin compared to healthy skin in pemphigus patients." (PMID 40051023, 2025). "The positive rates of anti-Dsg1, Dsg3, BP180 and BP230 antibodies were 68.5%, 63.0%, 9.3% and 0% in patients with pemphigus, and 1.89%, 0.94%, 76.42% and 37.74% in patients with BP, respectively." (PMID 40661962, 2025). "92.6% of pemphigus patients and 79.25% of BP patients were positive for at least one AIBD autoantibody (Dsg1, Dsg3, BP180, BP230)." (PMID 40661962, 2025). "The mechanism of pemphigus lies in the immune response targeting desmoglein 3 (DSG3) and, to a lesser extent, desmoglein 1 (DSG1)." (PMID 39727486, 2024). "We calculated the levels of DSG-1 and DSG-3 exclusively for the pemphigus patient group, consisting of 10 individuals." (PMID 38399557, 2024). "Risk factors for relapse include high body surface area (BSA) of pemphigus involvement, high body mass index, high severity according to the Pemphigus Disease Area Index (PDAI) at onset, treatment delay, and high anti‐DSG1 and DSG3 titers post‐treatment." (PMID 39460496, 2024). "Quantitation of specific anti-DSG1 and DSG3 antibodies can be achieved with DSG ELISA and facilitates pemphigus sub-typing." (PMID 38074463, 2023). "Overall, the depletion of DSG1 and DSG3 in pemphigus activates multiple signaling pathways, which contribute to the pathogenesis of this autoimmune disease." (PMID 37237515, 2023). "Mucocutaneous Pemphigus is determined by the presence of autoantibodies targeting both DSG3 and DSG1 and lesions in both sites." (PMID 37237515, 2023). "The most common forms of pemphigus are those characterized by the presence of autoantibodies against the cadherin DSG3 (affecting mainly the mucosae), the cadherin DSG1 (affecting mainly the epidermis), or both simultaneously (mucocutaneous)." (PMID 37237515, 2023). "Based on this distribution pattern of the Dsg3 and Dsg1 proteins, the DCH postulates 3 subtypes of pemphigus: Pemphigus foliaceus (PF), mucosal-limited Pemphigus vulgaris (PV), or mucocutaneous PV." (PMID 36211362, 2022). "Pemphigus is an autoimmune blistering disease (AIBD) of the skin and mucous membranes in which autoantibodies targeting cell-cell adhesion molecules (desmoglein 1 and 3) induce blister formation." (PMID 33936104, 2021). "We next investigated anti-Dsg1 IgG1 and IgG4 subclass levels by modulating a commercially available ELISA system (MBL), as these are known to represent the most abundant subclasses in pemphigus." (PMID 41459496, 2025). "In pemphigus, the presence of circulating anti‐Desmoglein‐1/3 (Dsg1 and Dsg3) autoantibodies in individuals without skin lesions indicates that additional factors, potentially including local immune responses, influence disease manifestation." (PMID 40051023, 2025). "Analyzing the subtypes of pemphigus, Dsg3 levels were significantly higher in patients with PV than in patients with PF, and Dsg1 antibodies also differed between the two, but not as significantly as Dsg3." (PMID 40661962, 2025). "There are numerous case reports of individuals with positive antibodies to Dsg1 and Dsg3 antigens without a pemphigus phenotype." (PMID 40098967, 2025). "Regardless of pemphigus subtype, autoantibody titre negativity at clinical remission in patients classified based on their anti‐Dsg1 and anti‐Dsg3 profile at diagnosis and BSA were useful tools in predicting relapse." (PMID 34288016, 2022).
pemphigus (continued). "We conclude that, although our model has only bi-specific anti-DSG1/DSG3 scFv, some ultrastructural hallmarks of desmosome morphology following Px4-3 binding are reproduced in our HSOC model, reflecting the lesional skin of pemphigus patients." (PMID 36452895, 2022). "Strangely, anti-desmoglein 1 antibodies were positive, although no pemphigus-like features were found." (PMID 35665215, 2022). "Pemphigus and BP are identified by both circulating and tissue-bound autoantibodies against desmosomal cadherins (mainly desmoglein 1 and 3 (DSG1/3) in pemphigus) and dermal–epidermal junction components (mainly hemidesmosomal proteins, e.g., BP180 and BP230 in BP)." (PMID 32235430, 2020). "Indeed, DSG1-positive and DSG3-positive B cells were detectable in HD, although at a lower frequency than in the 20 patients with active pemphigus (DSG1 positive 0.11 vs. 0.20%, p < 0.001; DSG3 positive 0.10% vs. 0.20%, p < 0.001)." (PMID 31440235, 2019). "Because of the different expression of the pemphigus autoantigens (Dsg1 and Dsg3) in the cornified and non-cornified epithelium, skin and mucosae are differentially affected by anti-Dsg IgG autoantibodies." (PMID 31293582, 2019). "It was shown that activation of Src was detectable only when PV-IgG fractions contained antibodies against Dsg3 but not when pemphigus foliaceus (PF) autoantibodies against Dsg1 were applied." (PMID 31024527, 2019). "The serological diagnosis of pemphigus relies on the detection of IgG autoantibodies directed against the epithelial cell surface by indirect immunofluorescence (IIF) on monkey esophagus and against desmoglein 1 (Dsg1) and Dsg3 by ELISA." (PMID 29740444, 2018). "There have also been reports of high Dsg1 and Dsg3 ELISA values despite the absence of disease activity as well as low levels despite a relapse of pemphigus." (PMID 29872685, 2018). "In pemphigus, serum anti-Dsg1 and Dsg3 autoantibodies levels were not related to peripheral CD19hi B cells either." (PMID 29066741, 2017). "The rather simple explanation of pemphigus’ pathogenesis through steric hindrance relies on the DSG compensation hypothesis, which states that the distribution of DSG1 and DSG3 in the epidermis determines the site of blistering in pemphigus skin." (PMID 28928733, 2017). "Neither was observed in pemphigus between the proportion of CD19hi B cells and anti-Dsg1 or anti-Dsg3 autoantibodies." (PMID 29066741, 2017). "IgA pemphigus is serologically negative for Dsg1,3 and IgA positive for Dsc." (PMID 40098967, 2025). "A 2018 study found that almost half of subjects in a population in Amazonian Peru had positive anti-Dsg1 antibodies and approximately 25% had positive anti-Dsg3 antibodies in the absence of pemphigus lesions, highlighting the role of environmental and ethnographic factors." (PMID 40098967, 2025). "The two most common subtypes of pemphigus include pemphigus vulgaris (PV), which primarily targets desmoglein 3 with mucosal involvement, as well as pemphigus foliaceous (PF), which primarily targets desmoglein 1, generally without mucosal involvement." (PMID 39355721, 2024). "Patient classification based on anti‐Dsg1 and anti‐Dsg3 autoantibody positivity at diagnosis, regardless of pemphigus subtype and subsequent assessment of antibody titres at clinical remission, may be of use in predicting relapses." (PMID 34288016, 2022). "Moreover, ADAM10 inhibition was shown to be protective in a murine pemphigus model when antibodies against Dsg1 and Dsg3, but not Dsc3, were present in the patient sera." (PMID 35844545, 2022). "Therefore, its pathogenic correlation has no direct connection with the level of anti-DSG1/DSG3 IgG nor anti-BP180/230 IgG in the serum of pemphigus and SABD patients, respectively." (PMID 32235430, 2020). "We hypothesize that levels of IgG autoAbs against TPO and/or AChRs from patients with pemphigus will not be correlated with clinical disease activity or levels of IgG autoAbs against DSG1 or DSG3." (PMID 32555697, 2020).
pemphigus (continued). "However, recent studies suggest that the presence of autoantibodies against DSG1 and DSG3 alone is not sufficient to fully explain the loss of cell-to-cell adhesion observed in pemphigus." (PMID 31275323, 2019). "However, the level of anti-Dsg-1 and anti-Dsg-3 antibodies, which play an important role in the pathogenesis of pemphigus did not present any significant difference among each period." (PMID 30083474, 2018). "Pemphigus is a group of chronic, rare, potentially life-threatening AIBD of the skin and/or mucous membranes characterized most commonly by autoimmunity against desmoglein (DSG) proteins, namely, DSG3 alone, DSG1 alone, or both DSG3/DSG1, but other antibodies may be involved in immunization." (PMID 37885886, 2023). "Thus, some authors claim that the combination of a Dsg1-rich substrate, such as guinea pig esophagus or human skin, and a Dsg3-rich substrate, such as monkey esophagus, is crucial prerequisite to increase the sensitivity of IIF when screening the sera of pemphigus patients." (PMID 30386780, 2018). "In addition to Dsg3 and Dsg1, several other organ-specific non-Dsg autoantibodies in pemphigus patient sera could be involved in an intermolecular ES phenomenon." (PMID 29719538, 2018). "While not currently a standard pemphigus therapy, INE effectively reduced Dsg1 and Dsg3 levels to normal, resolved symptoms, reduced Pemphigus Disease Activity Index scores, and allowed prednisone tapering to 5 mg per day." (PMID 41362865, 2026). "Although available tests for pemphigus-related autoantibodies (including BP180, BP 230, Dsg1, and Dsg3) were negative, the diagnosis of PNP was finally confirmed by the presence of pelvic tumor and positive tests of indirect immunofluorescence on rat bladder." (PMID 39473502, 2024). "Screening for pemphigus-related autoantibodies, including BP180, BP 230, Dsg1, and Dsg3, yielded negative results." (PMID 39473502, 2024). "Besides Dsg1 and 3, numerous other non-desmoglein autoantibodies found in PV targeting important proteins in physiology and cell adhesion, which may contribute to pemphigus pathogenesis." (PMID 33193387, 2020). "However, the effect of ADAM10 appeared to depend on the antibody profile, because ADAM10 inhibition was not protective in both the cell culture and ex vivo pemphigus skin models, when a PV-IgG from a different patient (PV4-IgG), containing high levels of anti-Dsg1 autoantibodies was used." (PMID 35844545, 2022).
pemphigus foliaceus (78 papers, 2006 to 2025). Pemphigus foliaceous is a rare superficial pemphigus disease characterized by multiple, pruritic, scaly, crusted cutaneous erosions, with flaky circumscribed patches, localized mostly on the face, scalp, trunk and extremities, often presenting an erythematous base. "Since PE is considered a variant of pemphigus foliaceus, scientists expect the presence of antibodies against DSG1 in the sera of these patients." (PMID 39860415, 2025). "In the endemic variants of pemphigus foliaceus (PF), in Brazil and Tunisia, patients generate pathogenic IgG4 anti-desmoglein 1 autoantibodies." (PMID 35693761, 2022). "Different expression patterns of Dsg3 and Dsg1 give rise to either the mucosal-dominant PV (Dsg3) or the primarily skin-associated pemphigus foliaceus (PF; Dsg1)." (PMID 36203615, 2022). "As pemphigus foliaceus (PF) is associated only with IgG autoantibodies against Dsg1, blistering is confined to the upper skin, while there is no apparent mucosal involvement." (PMID 31552014, 2019). "By contrast, in pemphigus foliaceus (PF), flaccid blisters are found in the skin only, and their formation is associated with the occurrence of anti-Dsg1 autoantibodies." (PMID 29449846, 2018). "In pemphigus foliaceus (PF), patients develop pathogenic autoantibodies that target Dsg1 and promote cell-cell disadhesion in the superficial epidermis, where Dsg1 is highly expressed, but which lacks Dsg3 and Dsg2." (PMID 20631906, 2010). "Future work will include autoantigens from Dsg1, the main causative agent for pemphigus foliaceus and reported in severe cases of PV." (PMID 16426456, 2006). "In pemphigus vulgaris (PV), autoantibodies mainly directed against Dsg1 and 3 cause suprabasal blistering of the epidermis and mucous membranes, whereas in pemphigus foliaceus (PF) autoantibodies directed against Dsg1 cause superficial blisters in the skin only." (PMID 33193387, 2020). "Mucosal-dominant pemphigus vulgaris (PV) is characterised by autoantibodies (PV-IgG) against Dsg3 whereas epidermal blistering in PV and pemphigus foliaceus (PF) is associated with autoantibodies against Dsg1." (PMID 34434944, 2021). "Pemphigus foliaceus (PF) is a rare autoimmune skin disease caused by anti-Dsg1 pathogenic autoantibodies." (PMID 30116153, 2018). "Fogo Selvagem (FS) in Limao Verde (LV), Brazil shows clinical and histological features of pemphigus foliaceus (PF) and shares pathogenic IgG4 anti-desmoglein 1 (Dsg1) autoantibodies." (PMID 25309813, 2014). "Skin biopsy findings and desmoglein 1 (DSG1)-IgG positivity were consistent with pemphigus foliaceus." (PMID 40995362, 2025). "Immunological phenomena in patients with PE include features typical of pemphigus foliaceus: the presence of anti-DSG1 antibodies and the erosions on the mucous membranes." (PMID 39860415, 2025). "In pemphigus foliaceus (PF), autoantibodies to desmoglein 1 (anti-Dsg1) in the IgG4 subclass of immunoglobulins played an opposite role by reducing FcγR-binding affinity or ablating FcγRs, which enhanced their pathogenic function." (PMID 39364411, 2024). "Pemphigus foliaceus (PF) is an acquired, rare, autoimmune skin condition associated with autoantibodies that specifically target desmoglein-1, leading to a clinical presentation characterized by delicate cutaneous blisters, typically sparing the mucous membranes." (PMID 39203983, 2024). "The autoantibody profiles with either anti-Dsg1 or anti-Dsg1 and anti-Dsg3 IgG largely correlate with the clinical phenotypes of pemphigus foliaceus (PF) or pemphigus vulgaris (PV) respectively." (PMID 39882246, 2024). "Characteristic for pemphigus foliaceus are desmoglein 1 (Dsg1)-specific auto-ab that induce sub-corneal blister formation in the epidermis." (PMID 39450179, 2024). "In PV and pemphigus foliaceus (PF), IgG autoantibodies are directed against components of desmosomes, namely desmoglein (Dsg) 3 and Dsg1." (PMID 37415985, 2023).
pemphigus foliaceus (continued). "Desmoglein 1 (Dsg1)-specific auto-abs induce subcorneal blister formation characteristic of pemphigus foliaceus." (PMID 37174740, 2023). "(A) Plots showing the unit values of indicated Dsg1-specific antibodies in the serum of pemphigus foliaceus (PF) patients (n=53)." (PMID 35920621, 2022). "Although the impaired intercellular adhesion observed in Dsg1–/– mice resembles that resulting from anti-Dsg1 pemphigus foliaceus antibodies, pemphigus skin lesions exhibit a weaker IL-17 signature." (PMID 34905516, 2022). "Among the different phenotypic variants encompassing this disease, Pemphigus vulgaris (PV) and Pemphigus foliaceus (PF), caused by the presence of autoantibodies against the desmosomal cadherins desmoglein 3 (DSG3) and 1 (DSG1), are the most common forms." (PMID 35806044, 2022). "Recently, in a patient with thymoma expressing Aire, the condition manifested as pemphigus foliaceus with anti-Dsg1 autoantibody." (PMID 31214197, 2019). "Usually, in pemphigus vulgaris a mucosal-dominant phenotype (m-PV) is paralleled by autoantibodies against Dsg3 whereas epidermal involvement in PV (mc-PV) is in addition associated with formation of autoantibodies against Dsg1 which can also be found in pemphigus foliaceus (PF)." (PMID 31178865, 2019). "Pemphigus foliaceus is an autoimmune skin disease mediated by autoantibodies directed against desmoglein-1 located in the upper epidermal layer." (PMID 30474029, 2018). "In pemphigus foliaceus (PF), autoantibody reactivity is limited to Dsg1 and patients only develop skin lesions." (PMID 30233569, 2018). "The endemic form (fogo selvagem—FS) of pemphigus foliaceus is an autoimmune disease characterized by the presence of IgG autoantibodies against desmoglein-1." (PMID 28855908, 2017). "In pemphigus vulgaris, the Ab are directed against desmoglein-3 and/or desmoglein-1 while in pemphigus foliaceus they are directed only against desmoglein-1." (PMID 26885437, 2016). "For instance, for patients with pemphigus foliaceus, an autoimmune blistering skin disease, IgG4 is the predominant antibody against desmoglein 1 and mediates the formation of cutaneous blisters." (PMID 25548435, 2014). "Autoantibodies to desmosomal proteins, DSG1 and DSC1 proteins are a hallmark of blistering skin conditions including pemphigus foliaceus and IgA pemphigus." (PMID 24497829, 2014). "BP180-Abs are associated with BP while desmoglein antibodies with pemphigus vulgaris (Dsg3-Abs) and pemphigus foliaceus (Dsg1-Abs)." (PMID 23781320, 2013). "In pemphigus foliaceus, autoantibodies form against Dsg1, which is expressed in the epidermis; while pemphigus vulgaris is characterized by autoantibodies against Dsg3, present in skin and mucous membranes, and in some subtypes also by anti-Dsg1." (PMID 23566679, 2013). "In such cases, PV may mimic other conditions like pemphigus foliaceus (PF), which primarily targets Dsg1 and typically presents with superficial erosions and crusting, sparing the mucous membranes." (PMID 40600094, 2025). "Interestingly, while morphological features of Dsg1-deficient epidermis resemble those found in human patients with pemphigus foliaceus (PF), the transcriptome of PF lesions showed weaker Th17 skewing than that resulting from targeting the Dsg1 gene." (PMID 34905516, 2022). "The potential cross-reactivity of some sand fly salivary gland proteins (LJM 17 and 11 in the NW and PpSP32 in the OW) with Dsg1, the autoantigen of endemic pemphigus foliaceus, indicates the need for a careful choice when selecting such proteins as candidates for anti-Leishmania vaccines." (PMID 35281450, 2022). "Desmoglein 1 also represents the major autoantigen in human pemphigus foliaceus." (PMID 32344723, 2020).